MGMT (O-6-methylguanine-DNA methyltransferase)
Diseases named in the same sentence as MGMT in open-access papers (continued):
Sharing a sentence is not in itself a finding about the gene and the disease.
colorectal cancer (continued). "Between February 19, 2020 and June 22, 2021, 62 patients with metastatic MSS colorectal cancer were screened for MGMT promoter hypermethylation, of which 51 had adequate tumor tissue for clinical grade MGMT testing by bisulfite deamination and MS-PCR." (PMID 37387791, 2023). "Our study represents the first clinical evaluation of TMZ plus a PARPi in MGMT promoter hypermethylated colorectal cancer." (PMID 37387791, 2023). "In contrast, previous observations for MGMT promoter hypermethylation in colorectal cancer were that these tumors are more likely to arise from serrated adenomas and serrated adenocarcinomas, which are less frequently APC-mutated." (PMID 37387791, 2023). "Considering all these things, we found it rational to investigate the correlation between the methylation status of ERCC1 and MGMT, prognosis, survival and therapeutic response in colorectal cancer patients." (PMID 37510370, 2023). "Here, we report the results of a single-arm, investigator-initiated, phase II clinical trial of TMZ in combination with olaparib in patients with MGMT promoter hypermethylated advanced colorectal cancer." (PMID 37387791, 2023). "Temozolomide showed a modest activity in colorectal cancers with MGMT promoter methylation and the corresponding clinical trial did not meet its primary end point." (PMID 32111026, 2020). "It was also reported that ALA induced autophagy via inhibition of O6-methylguanine-DNA methyltransferase (MGMT) protein, which consequently led to apoptosis and cytotoxicity to chemo-resistant colorectal cancer cells." (PMID 32344912, 2020). "In a colorectal cancer study it was suggested that MGMT expression reduced after hyper-methylation of the MGMT promoter region." (PMID 31754358, 2019). "Recently, the methylation status of MGMT has been correlated with pathologic complete response in colorectal cancer patients." (PMID 31199091, 2019). "The use of MGMT as a biomarker for determining temozolomide utility outside of brain tumors has shown promise in case reports of colorectal cancer patients with low MGMT expression." (PMID 28556593, 2017). "MGMT methylation is more frequent in the margins of lung and colorectal cancer tissue samples than in the most distant sites from the resected specimen." (PMID 26967246, 2016). "Methylation of MGMT gene promoter can diminish MGMT protein expression in tumor tissues of various types of cancers, including lung cancer, gastric cancer, colorectal cancer, and breast cancer." (PMID 27657735, 2016). "This suggests that MGMT methylation is a potential early detection marker for lung and colorectal cancers." (PMID 26967246, 2016). "MGMT field cancerization has, however, been detected in colorectal cancers and oral squamous cell carcinomas." (PMID 26370119, 2015). "The objective of this study was to determine the prognostic value of CD133 and MGMT and their possible interaction in colorectal cancer patients." (PMID 25015560, 2014). "Methylation of the O6-methylguanine-DNA methyltransferase (MGMT) gene promoter as well as of the P14ARF locus has been found in the normal-appearing colorectal mucosa adjacent to colorectal cancer." (PMID 24760232, 2014). "Jass has suggested a “fusion pathway” with overlapping features from the two major colorectal cancer pathways in which MGMT serves as a “cross-over” point." (PMID 24151575, 2013). "The focus of this perspective is the role of MGMT in different pathways of colorectal carcinogenesis as well as the implication of this molecule in treatment decisions in colorectal cancer patients." (PMID 24151575, 2013). "In summary, PIK3CA-mutated colorectal carcinomas are more likely to develop in the proximal colon, to demonstrate high levels of CIMP, KRAS mutation and loss of MGMT expression." (PMID 23785428, 2013).
colorectal cancer (continued). "In summary, we have found that PIK3CA mutation in colorectal carcinomas correlated with tumor proximal colonic location, mucinous differentiation, KRAS mutation, high levels CIMP and loss of MGMT expression." (PMID 23785428, 2013). "In contrast, the two genes MLH1 (the human homolog of the E. coli DNA mismatch repair gene mutL) and MGMT (O6-Methylguanine DNA methyltransferase) are hypermethylated in a number of different cancers, including colorectal cancer." (PMID 22243995, 2012). "In order to validate the accuracy of the RMEAM approach, we analyzed the MLH1, TERT and MGMT promoter methylation density in 18 colorectal carcinoma patients." (PMID 18237388, 2008). "We demonstrate a use of this method in determining the methylation density of the promoter region of the tumor-related gene MLH1, TERT and MGMT in colorectal carcinoma patients." (PMID 18237388, 2008). "Recently, evidence for field cancerization in colorectal cancer has been provided by analysis of promoter methylation in the DNA repair gene, O6-methylguanine-DNA methyltransferase (MGMT)." (PMID 17362521, 2007). "The aim of this study was to examine for the first time in a systematic manner, the topographical pattern of MGMT activity of normal mucosa around colorectal cancers and to determine the intra-individual variation in MGMT activity." (PMID 12107837, 2002). "Promoter hypermethylation of MGMT in colorectal carcinomas results in transcriptional inactivation of MGMT gene." (PMID 12085181, 2002). "The authors suggested that some colorectal cancers may arise from a field defect defined by epigenetic inactivation of MGMT." (PMID 40357388, 2025). "Surprisingly, they also observed a significant reduced risk of developing MGMT methylation–negative colorectal cancers." (PMID 39980037, 2025). "The anti-cancer activity of cannabinoids CBD and 4’-F-CBD was assessed against a vector control GBM cell line (U373-V) and two cell lines representing common resistance mechanisms to treatment with TMZ (U373-M, MGMT-transfected U373-V isogenic partner, and MMR-deficient HCT116 colorectal cancer)." (PMID 39516685, 2024). "Despite the analysis being conducted on a limited cohort of mCRC patients, the observed trend supports the idea that MGMT hypermethylation may play an important role in colorectal cancer." (PMID 39594133, 2024). "Together, these results suggest that MGMT protein can be expressed in a substantial fraction of MGMT promoter-methylated colorectal cancer, and low MGMT expression in tumor cells and increased local effector TILs were associated with benefit from TMZ and olaparib." (PMID 37387791, 2023). "Up to 40% of colorectal cancer is MGMT promoter hypermethylated, and we investigated whether TMZ and olaparib are effective in this population." (PMID 37387791, 2023). "The promoter methylation of ERCC1 and MGMT is an essential event in cancer progression, spread, relapse, and could be clinically useful in assessing colorectal cancer progression and survival." (PMID 37510370, 2023). "In addition to their role in cancer prevention, ERCC1 and MGMT genes were considered as markers for the therapeutic response of many types of cancer, including colorectal cancer." (PMID 37510370, 2023). "Therefore, our finding is potentially important from a clinical point of view, given the increasing body of evidence on efficacy for TMZ‐based regimens in MGMT‐methylated gastrointestinal tumors and especially colorectal cancer." (PMID 35621918, 2022).
colorectal cancer (continued). "Overall, the most frequently mutated drug target genes were BRAF for thyroid cancer, FGFR2 for endometrial cancer, EGFR for brain tumors, MGMT for colorectal cancer, FGFR2 and FGFR3 for bladder cancer, NTRK3 for non-small cell lung cancer and NTRK2, FGFR2, EGFR for stomach cancer." (PMID 32111026, 2020). "The relationship between MGMT and colorectal cancer remains unclear, and results have been contradictory." (PMID 31199091, 2019). "MGMT has been associated with several cancers like colorectal cancer and lung cancer, but its function in ICH has not been reported previously, so clinical experiments are needed to verify the results of this research." (PMID 28450824, 2017). "MGMT has been reported as a tumor suppressor gene in colorectal cancer." (PMID 27824946, 2016). "Similar results were obtained in colorectal cancer by treating MGMT methylated patients with TMZ." (PMID 26967246, 2016). "Aberrantly methylated levels of APC and MGMT were also observed in colorectal cancer tissues." (PMID 26862903, 2016). "Moreover, the methylation of MGMT was also reported as a valuable molecular marker for the early detection of colorectal cancer." (PMID 26148869, 2015). "Hypermethylation of the MGMT promoter region can silence its expression and result in a deficiency in MGMT-mediated DNA repair and is most frequently detected in high-grade glioma (HGG) and colorectal carcinomas." (PMID 25211033, 2014). "KRAS codon 12/13 and 59/61 and BRAF V600E mutations, MSI, and MGMT and hMLH1 methylation and expression in 42 serrated adenocarcinomas and 17 serrated adenomas were compared with those in 59 non-serrated colorectal carcinomas (CRCs) and nine adenomas." (PMID 21457162, 2011). "We have found an association between low levels of MGMT activity in adjacent normal mucosa and GC→AT transition mutations, but not transversion mutations, in K-ras of colorectal cancers." (PMID 12107837, 2002). "Finally, expanding the scope of KL-50 to include extracranial malignancies with MGMT silencing, such as colorectal cancer and other oncometabolite-driven tumors, may further broaden the clinical application of this novel class of agents." (PMID 41169667, 2025). "Thus, MGMT promoter hypermethylated colorectal cancer may be heterogenous in development compared with the conventional development of adenomatous polyps." (PMID 37387791, 2023). "Another study has shown that MGMT rs16906252 promoter SNP is strongly associated with MGMT promoter methylation and loss of expression in colorectal cancer, and with MGMT methylation in peripheral blood cells and normal colonic mucosa in individuals without colorectal cancer." (PMID 21738611, 2011). "It has been reported that DNA methylation of the genes MGMT and WNT5A indicates an excellent response to 5‐FU‐based therapy in colorectal cancer." (PMID 38778448, 2024). "The methylation of MGMT, alone or combined with ERCC1, is predictive for poor prognosis, short overall survival and chemotherapy response in colorectal cancer." (PMID 37510370, 2023). "Currently, the expression of DNA repair genes such as the enzyme O-6-methylguanine-DNA methyltransferase (MGMT) and Excision Repair Cross-Complementation Group 1 (ERCC1) plays a potential role in colorectal cancer progression." (PMID 37510370, 2023). "Approximately 40% of colorectal cancer has MGMT silencing and we aimed to measure antitumoral and immunomodulatory effects from TMZ and olaparib in colorectal cancer." (PMID 37387791, 2023). "The enzyme O6-methylguanine-DNA methyltransferase (MGMT), which eliminates methyl groups in the O6-guanine position avoiding G:C to A:T transitions, has also been related to colorectal cancer." (PMID 31199091, 2019).
colorectal cancer (continued). "MGMT was a DNA-repair gene, which greatly contributed to the microsatellite instability (MSI) in colorectal cancer." (PMID 26862903, 2016). "Results suggest a gradual expansion of methylation across CpG islands in MGMT, RASSF2, and SFRP2 promoters during colorectal cancer progression and highlighted their potential role as biomarkers for diagnosis and disease prediction for specific cancer types." (PMID 27095449, 2016). "Immunohistochemical analysis of MGMT and CD133 expression was carried out in colorectal cancer samples from 123 patients, and MGMT methylation status was determined by methylation-specific PCR (MSP)." (PMID 25015560, 2014). "O6-methylguanine DNA methyltransferase (MGMT) methylation and protein expression have been related to colorectal cancer treatment failure and tumor progression." (PMID 25015560, 2014). "The present study analyzed and compared the levels of MGMT and MLH1 gene methylation in the leukocytes of peripheral blood and colorectal tissues obtained from patients with colorectal cancer (CRC)." (PMID 24179526, 2013). "A number of genes are commonly hypermethylated in colorectal cancer (CRC) including hMLH1, p16INK4a, p14ARF, RAR-β, APC, MGMT, cyclin A1, CDX1, MYOD1, COX-2 and WT-1." (PMID 19662090, 2009). "In the same study, a substantial number of colorectal cancer patients showed MGMT methylation in both macroscopically normal mucosa and matching carcinomas." (PMID 40357388, 2025). "These cell lines do not possess MGMT over-expression or MMR deficiency that comprise major GBM resistance mechanisms to TMZ, represented in this work by human GBM U373-M and colorectal cancer HCT116 cell lines, respectively." (PMID 39516685, 2024). "Comparable findings are described by other groups showing that MGMT promoter hypermethylation is necessary but not sufficient for TMZ sensitivity for colorectal cancer." (PMID 37387791, 2023). "Based on the published clinical activity of TMZ in MGMT methylated colorectal cancers, four patients with no other therapeutic options were treated at INT with TMZ‐based therapies from December 2018 until September 2019." (PMID 35621918, 2022). "Epigenetic abnormalities may serve as a marker of a “field defect”, such as MGMT, p16 and RASSF1A promoter region methylation in normal-appearing mucosa of colorectal cancer patients." (PMID 31695915, 2019). "The evidence supporting the predictive role of gene/protein expression of TYMS–5FU/Capecitabine in colorectal cancers, TUBB3-taxanes in NSCLC and MGMT–temozolomide in brain tumors was modest and mainly from level III observational studies and level IV pre-clinical studies." (PMID 27888622, 2017). "So far, field cancerization due to MGMT promoter methylation has been reported for colorectal cancers and oral squamous cell carcinomas, but not for breast cancer." (PMID 26370119, 2015). "However, the MGMT promoter methylation yielded no benefit from 5-fluorouracil or oxaliplatin-based regimens in colorectal cancer." (PMID 39055560, 2024). "Moreover, this study did not restrict enrollment to MGMT promoter hypermethylated colorectal cancer as our study did, nor did it analyze MGMT expression and TILs." (PMID 37387791, 2023). "Similarly, both MGMT promoter hypermethylation and reduced/absent MGMT expression are described in a variety of gastrointestinal malignancies, including colorectal cancers." (PMID 35621918, 2022). "However, the role of MGMT promoter methylation status as an early biomarker of colorectal cancer has not yet been established, despite several studies in colorectal adenoma and adenocarcinoma." (PMID 31199091, 2019).
colorectal cancer (continued). "Thus, MGMT and CD133 may both be useful for determining the prognosis of colorectal cancer patients and to identify those requiring more aggressive adjuvant therapies." (PMID 25015560, 2014).
brain tumors (94 papers, 2010 to 2026). "MGMT is overexpressed in approximately 80% of human brain tumors and is strongly associated with TMZ resistance, particularly in GBM." (PMID 40835840, 2025). "Taken together, our findings support the theme of inducing an MGMT deficient state through redox-altering agents for improving brain tumor treatment." (PMID 39997039, 2025). "Additional predictive markers such as the methylation status of the O-6-methylguanine-DNA-methyltransferase (MGMT) promotor further help to stratify brain tumor patients according to their individual risk profile." (PMID 36227357, 2023). "Here, we used a long-read nanopore-based sequencing technique to simultaneously assess IDH mutation status and MGMT methylation level in 4 human cell lines and 8 fresh human brain tumor biopsies." (PMID 32563269, 2020). "With regard to extracranial metastasis among other primary brain tumors, MGMT promoter hypermethylation has been associated with ECM in oligodendrogliomas." (PMID 26199775, 2015). "In fact, diagnostic accuracy estimates for MGMT protein expression by IHC were significantly lower for brain tumours than for other non-brain tumours (sensitivity, 53-64% vs. 60-81% respectively; specificity, 60-84% vs. 80-93% respectively)." (PMID 21269507, 2011). "In brain neoplasms, hypermethylation of CpG islands in the MGMT gene promoter region, rather than mutation or deletion, is the major mechanism for the loss of MGMT function." (PMID 21269507, 2011). "MGMT protein expression by IHC for brain tumours is associated with a more than four-fold lower accuracy compared to other tumours (RDOR 4.38; 95% CI[1.82-10.54], p = 0.0017)." (PMID 21269507, 2011). "However, human cancers including brain tumors express the MGMT protein in abundance; a large fraction of CNS malignancies, nevertheless are MGMT-deficient due to gene silencing by promoter methylation." (PMID 33801310, 2021). "Dose-restrictive and primarily myelosuppressive toxicity, as well as tumor tolerance towards alkylating compounds, mainly via the nucleotide repair enzyme MGMT (O6-methylguanine-DNA methyltransferase), are further problems associated with the successful management of brain tumors." (PMID 34063122, 2021). "Although administration of ddTMZ regimens causes more pronounced depletion of MGMT in peripheral blood mononuclear cells, the effects of ddTMZ on MGMT activity in brain tumor tissue and its impact on clinical outcome remain unclear." (PMID 22396071, 2012). "Of importance, this was accompanied by a significant reduction of CCND1 and of MGMT expressions in the core of mice brain tumors (TM) thereby corroborating, in an integrated context, data obtained in vitro." (PMID 40108111, 2025). "In this section, we present both the quantitative and qualitative results of MGMT-Net in the context of brain tumor segmentation and molecular marker prediction." (PMID 41007223, 2025). "According to the data from the HPA databases, MGMT is highly expressed in 50% of brain tumor cell lines." (PMID 40429865, 2025). "Specifically, the measurement of MGMT promoter methylation (MGMTp testing) has proven to be a robust way to predict which brain tumor patients will respond to chemotherapy." (PMID 38791984, 2024). "When we analyzed the somatic mutations of genes related to brain tumor development, such as ARTX, BRAF, and MGMT, we identified more mutations in the PDX samples than in the original tumors." (PMID 38001935, 2023). "GBMs exhibiting a molecular profile with unmutated IDH1 and an unmethylated MGMT gene promoter tend to recur in most cases, contributing to the poor prognosis of this brain tumor." (PMID 37630276, 2023). "O6-methylguanine-DNA methyltransferase (MGMT), a unique antimutagenic DNA repair protein, has been reported to be overexpressed in brain tumors." (PMID 37376016, 2023).